CXCR2 (C-X-C motif chemokine receptor 2)
Diseases named in the same sentence as CXCR2 in open-access papers (continued):
Sharing a sentence is not in itself a finding about the gene and the disease.
tumor (continued). "High expression levels of CXCR2 in tumor cells are often associated with malignant progression, angiogenesis, metastasis, and immune evasion in tumors." (PMID 40006729, 2025). "The CXCL5/CXCR2 axis has been implicated in promoting tumor development, angiogenesis, and the activation of host cells." (PMID 39670859, 2025). "A recent study demonstrated a significant positive association between neutrophil count and tumor MDSC infiltration in patients with metastatic CRPC after treatment with another CXCR2 antagonist." (PMID 38324085, 2024). "We show that tumor-associated neutrophils not only respond to IL1β/CXCR2 in their environment but equally signal through IL1β and CXCR2 in an autocrine fashion." (PMID 38358352, 2024). "Another study found PMN-MDSCs were the dominant infiltrating immune cell type in a prostate adenocarcinoma model driven by loss of Pten and Smad4 and pharmacologic inhibition of CXCR2 impeded tumor progression." (PMID 38786066, 2024). "In conclusion, we showed that partial irradiation combining LDRT + HDRT, associated with the blockade of PD1 and CXCR2 was a potent way to promote anti-tumor activity, leading to several complete responses." (PMID 39397001, 2024). "The interaction between CXCL1 and the abundance of CXCR2 on neutrophils leads to the accumulation of tumor-associated neutrophils (TANs) at these sites." (PMID 38474175, 2024). "The endpoint of Lineage 4 (Cluster 5) was enriched for the chemokine CXCL8, the major ligand for G-Protein coupled receptor CXCR2 and associated with immune suppression and tumor progression in this context." (PMID 38358352, 2024). "These factors activate the CXCL1/CXCR2 feedback loop, leading to increased recruitment of tumor-associated neutrophils (TANs) and granulocytic myeloid-derived suppressor cells (G-MDSCs)." (PMID 39409924, 2024). "Recently, it has been shown that following the ligation of these chemokines, such as CXCL1 to CXCR2, tumor-associated immune cells can recruit into the tumor milieu to suppress anti-tumor immune responses and also activate the angiogenic processes." (PMID 38515019, 2024). "The IL1’/CXCL8/CXCR2 axis has been implicated in several tumor types and plays a role in neutrophil recruitment." (PMID 38358352, 2024). "Neutrophils and MDSCs predominantly express CXCR2 and play crucial roles in their mobilization and subsequent tumor-associated activities." (PMID 38750114, 2024). "CXCL7 from MSCs interacts with cancer cells via the IL-8 receptor, also known as C-X-C chemokine receptor type 2 (CXCR2), causing tumors to further synthesize IL-6 and IL-8 (another cytokine involved in tumor-tropism)." (PMID 38169524, 2024). "CXCR2 inhibits proliferation in normal cells, whereas its presence in the tumor microenvironment is associated with increased tumor cell proliferation." (PMID 38324085, 2024). "IL-8 signaling through CXCR2 recruits MDSCs to the tumor side, which can cause resistance to anti-PD1 therapy by inhibiting T-cell infiltration and activation." (PMID 37849764, 2023). "In conclusion, we provide evidence that CXCR2 blockade inhibits senescence-associated, tumour-elicited myeloid inflammation, with this blockade reversing ARSI resistance to confer durable antitumour activity in a subset of patients with mCRPC." (PMID 37844613, 2023). "CXCL8, mainly secreted by tumor-associated macrophages, can activate the NF-κB signaling pathway in endothelial cells via a CXCR2-dependent manner." (PMID 37765018, 2023). "We observed that loss of Cxcr2 activity in tumor cells resulted in a change in the tumor immune microenvironment, with increased CD8 + T cells and reduced macrophages and MDSC-like cells." (PMID 37270599, 2023). "A recent study shows that CXCR2-positive neutrophils infiltrate NASH-HCC models, and anti-PD-1/CXCR2 inhibitor combination therapy reprograms tumor-associated neutrophils (TANs)." (PMID 38022519, 2023).
tumor (continued). "RET/PTC rearrangements, implicated in HT, activate pathways that induce both HT and the expression of genes like CXCL5 and CXC chemokine receptor 2 (CXCR2), linked to inflammation and tumor invasion." (PMID 38317709, 2023). "The CXCR1/CXCR2 signaling nexus directly influences the sensitivity of tumor cells to chemotherapies by altering pathways associated with apoptosis and multidrug resistance, resulting in a poor prognosis in human cancer studies." (PMID 37270599, 2023). "CXCL1 acts on CXCR2+ macrophages in the tumor niche in prostate tumors, which causes stronger M2 polarization of these cells." (PMID 37108425, 2023). "The CXCR2 expression has been linked to the recruitment of a variety of immune cells to the tumor microenvironment and to an unfavorable outcome in multiple types of cancer." (PMID 36992360, 2023). "Angiogenesis is difficult to target because it can be triggered by tumor cells through an increase in CXCR2 agonism, or by a change in the cellular tumor infiltrate that favor tumor-associated macrophages." (PMID 37006247, 2023). "It has been demonstrated that higher levels of CXCR2 expression are associated with an increase in tumour size in pancreatic adenocarcinoma and a worse prognosis in a range of cancer types." (PMID 36902776, 2023). "To better understand the association between CXCL6/CXCR2 signaling and the tumor-promoting anti-inflammatory M2 phenotype of TAMs, we used an in vitro coculture system consisting of Huh7 cells and macrophages." (PMID 37509721, 2023). "In GC, the CXCR2 expression was associated with poor tumor differentiation, increased tumor depth, lymph node metastasis and a short overall survival." (PMID 36992360, 2023). "On the other hand, one study indicates that increased CXCR2 expression in the tumor is associated with a worse prognosis for patients with intrahepatic cholangiocellular carcinoma." (PMID 37408240, 2023). "It was reported that a higher infiltration of tumor-associated neutrophils (TANs) expressing IL-8RB/CXCR2 upon neoadjuvant treatment with the vaccine GVAX and nivolumab was associated with poorer survival." (PMID 37895882, 2023). "Through its interaction with ligands, CXCR2 mediates a powerful chemotaxis that is associated to tumor progression, angiogenesis, invasion, metastasis and chemoresistance." (PMID 35053602, 2022). "In situ hybridation analysis of Cxcr2 expression in DEN/ALIOS mouse tumours confirmed expression of Cxcr2 to be specifically associated with morphologically identified infiltrating neutrophils and absent in parenchymal and tumour cells." (PMID 35477863, 2022). "KRAS signaling is also thought to activate CXCL2 and its associated receptor CXCR2 resulting in suppressed immune response and tumor proliferation." (PMID 36033462, 2022). "On the contrary, delayed anti-PD1 treatment showed limited benefits associated with CXCR2+ myeloid cell recruitment in response to tumor secreted CXCL8." (PMID 35664746, 2022). "Consistently, CXCR2 inhibitors can reduce tumor-associated NETs in models of melanoma, breast cancer, and colorectal cancer." (PMID 35522219, 2022). "CXCR1 and CXCR2 are widely expressed on neutrophils, endothelial cells, cancer cells, and tumor-associated macrophages." (PMID 36072669, 2022). "Higher CXCR2 expression in tumor samples reduced the risk of recurrence in both the TA and TAc groups (univariate test: OR 0.0176, 95% CI [0.001–0.456], p = 0.015; multivariate test: OR 0.003, [0–0.508], p = 0.026)." (PMID 36140779, 2022). "Among the cells that shape the TME, tumor cells, immune cells, and cancer-associated fibroblasts are the main producers of CXCR2 chemokines." (PMID 35328639, 2022). "Conversely, inhibitors of CXCR2 have been shown to reduce tumor-associated neutrophil functions such as NETs in melanoma." (PMID 36295558, 2022).
tumor (continued). "Possibly, other neutrophil-attracting chemokines (such as CXCR4) compensated for the loss of CXCR2 in this experimental setting and attracted pro-angiogenic neutrophils into the tumor tissue." (PMID 35158807, 2022). "CXCR2 chemokines are produced by tumor cells, immune cells, and cancer-associated fibroblasts (CAFs)." (PMID 36226048, 2022). "The association of CXCR2 with senescence is important in the tumor microenvironment, as CXCR2 ligands secreted by cancer cells induce senescence of cancer-associated fibroblast (CAF)." (PMID 35216283, 2022). "A recent preclinical study suggested that an anti-PD1 and CXCR2 inhibitor combination selectively reprograms tumor-associated neutrophils from a pro-tumor to an anti-tumor phenotype that can overcome the resistance of NASH-HCC to anti-PD1 therapy." (PMID 35804984, 2022). "In this context, IL-8 induction by SMAD4 knock-down results in neutrophil recruitment into the TME via the IL-8 receptor CXCR2; these tumor-associated neutrophils (TAN), in turn, overexpress IL-8 when compared to peripheral blood neutrophils." (PMID 36289899, 2022). "CXCR2 is also important in tumor-associated neutrophils (TAN) recruitment, with pro-tumorigenic N2 neutrophils showing increased CXCR2 expression relative to N1 polarized neutrophils." (PMID 35216283, 2022). "Neutrophils express chemokine receptors CXCR1 and CXCR2 56, and tumor cells express the ligands of these receptors, thereby promoting the recruitment of tumor associated neutrophils." (PMID 36276645, 2022). "CXCR2 is a key regulator of immune suppression and inflammation in tumor microenvironment and plays crucial role in driving tumor associated macrophage (TAMs) polarization." (PMID 34831316, 2021). "Based on the literature database, there is no study comparing the diagnostic criteria for serum CXCL8 and CXCR2 levels with well-established tumor markers and CRP as GC biomarkers." (PMID 34680333, 2021). "The mechanisms by which the CXCR2–CXCLs axis promotes tumor progression are many, but the most notable is linked to the recruitment of neutrophils into the TME and the promotion of angiogenesis." (PMID 34575965, 2021). "Binding with CXCR2 (encoded by the CXCR2 gene) facilitates cell migration and is therefore reported to play a vital role as a receptor for tumor metastasis." (PMID 34066014, 2021). "Reciprocally, tumor-associated macrophages highly express CXCR2, HB-EGF, AREG, and ADAM proteinases, but EGFR is only weakly expressed." (PMID 33941851, 2021). "Epithelial to mesenchymal transition (EMT) is thought to be closely associated with tumor metastasis, and CXCR2 is reported to regulate cellular EMT." (PMID 33814009, 2021). "In a breast cancer mouse model, metastasis of tumor cells to lung is abolished by inhibiting CXCR2, which is associated with reduced recruitment of neutrophils." (PMID 34359674, 2021). "The expression of CXCR2 and CXCR2-associated chemokines of tumor cells were significantly increased following cisplatin stimulation." (PMID 33814009, 2021). "There is clear evidence of the role played by CXCR2 and its associated ligands not only in promoting tumor proliferation but also in modulating blood vessel formation and neutrophil recruitment to the site of the tumor." (PMID 34124076, 2021). "We compared the diagnostic utility of serum levels of CXCL-8 and CXCR-2 with classical tumor markers (CEA) for CRC." (PMID 34071492, 2021). "While CCR2/CCR5 can regulate the density of TAMs in the TME, another signaling protein present on MDSCs, CXCR2, is known to control chemotaxis of tumor-associated neutrophils." (PMID 34771675, 2021). "It has been reported that the activation of the CXCR1/CXCR2 or CXCR4/CXCR7 pathways is associated with tumor aggressiveness and poor prognosis." (PMID 34233297, 2021). "In multiple cancer types, CXCR2 is also known for recruitment of tumor associated neutrophils (TANs) to the TME." (PMID 34831316, 2021).
tumor (continued). "For example, CXCL1 together with its receptor CXCR2 were implicated in assisting with the homing of neutrophils into the tumor microenvironment in OS." (PMID 34225733, 2021). "In the present study, loss of expression of Cxcr2 leads to a pro-tumorigenic effect with not only an increase in the growth of the primary tumor, but also a higher rate of development of lung metastases." (PMID 34070438, 2021). "The diagnostic accuracy (ACC) of CXCL8 (77%) was higher than CXCR2 (70%) and classical tumor markers, CEA (48%) and CA19-9 (66%), but lower than for CRP (79%)." (PMID 34680333, 2021). "Mouse models of PDA show that tumor-associated neutrophils are recruited to the TME via the CXCR2/ligand axis and can coordinate immunosuppression and limit T cell infiltration into tumors." (PMID 33497362, 2021). "Associations of CXCR2 expression with immune checkpoints, neoantigens, tumor mutational burden (TMB), and microsatellite instability (MSI) were evaluated across pancancer." (PMID 34840630, 2021). "These cells also express high levels of Cxcr2 and Cxcl2 genes, which are associated with tumor progression and metastasis." (PMID 32719347, 2020). "Recent studies have shown that the CXCL1/CXCR2 signaling pathway regulates the inflammatory response; moreover, the pathway causes tumor cell proliferation, angiogenesis, and lymph angiogenesis and promotes tumor invasion and vascular metastasis." (PMID 32190668, 2020). "Inhibition of the CXC chemokine receptor 2 (CXCR2), a major receptor for IL-8, also led to decreased neutrophil presence in tumors and was associated with tumor suppression." (PMID 33363012, 2020). "Recent studies have confirmed that inhibition of CXCR2 signalling can repress the activity of myeloid-derived suppressor cells and re-educate the differentiation of tumour-associated macrophages in genetically engineered mouse models." (PMID 32743555, 2020). "Molecular-mediated and pharmacological-based inhibition of CXCR1/CXCR2 signalling sensitized each of the three PTEN-deficient tumour models to clinically relevant doses of IR." (PMID 32743555, 2020). "Considering the characteristic expression of CXCR1 and CXCR2 on cancer cells, endothelial cells, and tumor-associated macrophages, the increased secretion of IL-8 from tumor cells has significance to the tumor microenvironment." (PMID 32655554, 2020). "Other controversies include the characterization of CXCR2 in cancer cell senescence, and its role in Akt-associated tumor metastasis." (PMID 31788042, 2019). "Upregulation of the CXCR2-axis in PDAC is associated with tumor-supporting inflammation, immunosuppression, angiogenesis, and tumor growth." (PMID 30832219, 2019). "CXCR2 serves an important role in various aspects of breast cancer, including the diverse range of pathological processes associated with tumor progression." (PMID 31788042, 2019). "To harness tumor-derived IL-8 for therapeutic benefit, we have co-expressed either of its cognate receptors (CXCR1 or CXCR2) in CAR T-cells that target the tumor-associated αvβ6 integrin." (PMID 31091832, 2019). "Second, chemokines released from tumor-associated LECs attract CXCR2-positive MDSCs to create an immunosuppressive microenvironment." (PMID 31390756, 2019). "SNAIL is highly expressed in NSCLC, and the up-regulation of SNAIL is associated with poor prognosis by promoting tumor progression via the CXCR2 axis." (PMID 31297035, 2019). "As a member of the seven transmembrane G-protein-coupled receptor family, CXCR2 and its associated ligands have been increasingly implicated in tumor-associated processes." (PMID 31788042, 2019). "Triple-negative breast cancer (TNBC) cells secrete CXCL8, which activates CXCR2 in tumor-associated fibroblasts and tumor-associated macrophages." (PMID 31788042, 2019). "In CXCR2-deficient tumor-bearing mice, GMPs exhibited fewer macrophage and dendritic cell progenitor cells than wild-type tumor-bearing mice, thereby decreasing monocytic MDSCs (mo-MDSCs) expansion." (PMID 31395859, 2019).
tumor (continued). "Multiple cell types within the tumor produce the CXCR2 chemokines including tumor cells, immune cells, and cancer-associated fibroblasts." (PMID 31010242, 2019). "Our results showed that SAP18 expression was not affected by a CXCR2 deficiency in normal mice; however, SAP18 expression was increased when CXCR2 was deficient under tumor conditions." (PMID 31395859, 2019). "Next, as CXCR2 is a well-known player in cancer cell survival and tumor angiogenesis, we wanted to examine how loss of host Cxcr2 influences the in situ cell proliferation and microvessel density in the tumor-bone interface." (PMID 30871004, 2019). "Presence of high levels of macrophages (CD68) associated with CXCR2 positive cells (p=0.018) and when these were both present in high numbers in both sites associated with stromal phenotype (p=0.021), tumour budding (p=0.002) and worse prognosis (p=0.002)." (PMID 31591445, 2019). "In a preclinical model of spontaneous prostate cancer, tumor growth was significantly suppressed in CXCR2-deficient mice compared with controls, with a corresponding reduction in tumor angiogenesis as measured by von Willebrand factor RNA expression." (PMID 30800123, 2019). "Tumor cell-specific apoptosis is caused by the interaction between CXCR2 and its ligands, leading to limited tumor growth." (PMID 31024531, 2019). "In contrast, pancreas epithelial-specific loss of Cxcr2 induced recruitment of neutrophils and MDSCs into the tumor nest and enhanced PDAC metastasis." (PMID 30659170, 2019). "CXCR2 deficiency increased SAP18 expression in tumor-bearing mice, which reduced STAT3 phosphorylation through restraining ERK1/2 activation." (PMID 31395859, 2019). "LLC tumor angiogenesis (as quantified by microvessel density) was inhibited in CXCR2-deficient mice or WT mice treated with anti-CXCR2 mAbs vs. controls, which correlated with increased necrotic area and reduced tumor growth in vivo." (PMID 30800123, 2019). "CXCL5 is a chemokine that can recruit not only neutrophils, but also CXCR2+ myeloid-derived suppressor cells (MDSCs) and CXCR2+ monocytes that can be precursors of tumor-associated macrophages (TAMs)." (PMID 31080803, 2019). "SMAD4-deficient CRC cells also produce C-X-C motif chemokine ligand CXCL1/8 to recruit its corresponding receptor CXCR2+ tumor-associated neutrophils (TAN)." (PMID 31756952, 2019). "Our observation was that CXCR1 was uniformly expressed in tumor-associated microvessels in GBM while CXCR2 expression was limited to tumor cells." (PMID 30086759, 2018). "It has been proven that low expression of CXCR2 was associated with increased tumor necrosis and the CXC chemokines receptors played a critical role in tumor either." (PMID 29599927, 2018). "Experimental studies have shown that anti-programmed cell death protein 1 (PD1) and anti-cytotoxic T lymphocyte-associated antigen 4 (CTLA4) synergizes with anti-CXCR2 or anti-Ly6G, respectively, to delay tumour growth." (PMID 30304046, 2018). "This process was mediated by signaling through CXCR2 in neutrophils, consistent with the observation that neutrophil recruitment and tumor progression are impaired in Cxcr2-deficient mice in several models of carcinoma." (PMID 30356678, 2018). "We performed a meta-analysis to determine the association between the CXCR2 expression in tumor tissue and patient prognosis." (PMID 29312644, 2017). "Strategies explored to inhibit neutrophils include the inhibition of CXC receptors like CXCR2 that are associated with the migration of neutrophils to tumor areas." (PMID 28810877, 2017). "High expression of CXCR2 was associated with Dukes stage (P = 0.018), tumor invasion (P = 0.018) and liver metastasis (P = 0.047)." (PMID 28415702, 2017). "It has been reported that CXCL1/CXCR2 density is strongly associated with the number of neutrophils in the tumor microenvironment and can be an independent factor for predicting the prognosis of patients with hepatocellular carcinomas." (PMID 27446967, 2016).